TSEN15 (tRNA splicing endonuclease subunit 15)
Description:
Non-catalytic subunit of the tRNA-splicing endonuclease complex, a complex responsible for identification and cleavage of the splice sites in pre-tRNA. It cleaves pre-tRNA at the 5' and 3' splice sites to release the intron. The products are an intron and two tRNA half-molecules bearing 2',3' cyclic phosphate and 5'-OH termini. There are no conserved sequences at the splice sites, but the intron is invariably located at the same site in the gene, placing the splice sites an invariant distance from the constant structural features of the tRNA body. The tRNA splicing endonuclease is also involved in mRNA processing via its association with pre-mRNA 3'-end processing factors, establishing a link between pre-tRNA splicing and pre-mRNA 3'-end formation, suggesting that the endonuclease subunits function in multiple RNA-processing events.
Synonyms: C1orf19; SEN15; PCH2F
Tractability: PROTAC: its protein half-life has been measured.
Gene: Protein-coding gene on chromosome 1 (184,051,651 to 184,123,978, forward strand). Ensembl gene ENSG00000198860.
Subcellular location: Nucleus; Nucleus, nucleolus
Subcellular location (Human Protein Atlas): Nucleoli; Nucleoplasm
Pathways (Reactome):
Metabolism of RNA: tRNA processing in the nucleus
Gene Ontology:
Molecular function: protein binding; nucleic acid binding
Biological process: tRNA-type intron splice site recognition and cleavage; tRNA splicing, via endonucleolytic cleavage and ligation
Cellular component: tRNA-intron endonuclease complex; nucleoplasm; nucleolus; nucleus
Genetic constraint (gnomAD): Loss-of-function variants: 7 observed, 11.78 expected, observed/expected ratio (o/e) 0.59, 90% interval 0.34 to 1.12. The upper end of that interval is the gene's LOEUF score, 1.12, which puts it in group 4 of 6, group 1 being the genes least tolerant of losing a copy. Missense variants: 127 observed, 143.43 expected, observed/expected ratio (o/e) 0.89, 90% interval 0.77 to 1.03. Synonymous variants: 49 observed, 51.78 expected, observed/expected ratio (o/e) 0.95, 90% interval 0.75 to 1.2.
Homologues: Orthologues: chimpanzee TSEN15 (99% identical), macaque TSEN15 (99% identical), mouse Tsen15 (91% identical), rat Tsen15 (91% identical), guinea pig TSEN15 (88% identical), pig TSEN15 (87% identical), dog TSEN15 (66% identical), tropical clawed frog tsen15 (42% identical), zebrafish tsen15 (35% identical).
Diseases named in the same sentence as TSEN15 in open-access papers:
TSEN15 is named in the same sentence as 7 diseases in open-access papers, as found by Europe PMC text mining. Sharing a sentence is not in itself a finding about the gene and the disease. The quoted sentences say what the papers report.
microcephaly (1 paper, 2021). A congenital or acquired developmental disorder in which the circumference of the head is smaller than normal for the person's age and sex. "Researchers have reported that mutations in TSEN15 cause neurogenetic disorders, including progressive microcephaly and pontocerebellar hypoplasia, which suggest its importance in brain development." (PMID 34017855, 2021).
osteoarthritis (1 paper, 2023). A noninflammatory degenerative joint disease occurring chiefly in older persons, characterized by degeneration of the articular cartilage, hypertrophy of bone at the margins and changes in the synovial membrane. "Over 100 DNA variants have been associated with osteoarthritis (OA), including rs1046934, located within a linkage disequilibrium block encompassing part of COLGALT2 and TSEN15." (PMID 36538011, 2023).
Stroke (1 paper, 2023). Sudden impairment of blood flow to a part of the brain due to occlusion or rupture of an artery to the brain. "Multiple variants in the SLCO1B1, PRIM1, APOB, TYK2, TSEN15, CYP4F2, and MST1 genes were previously suggested as risk factors for stroke with p-values < 1.0 × 10−5 in a GWAS on German pediatrics." (PMID 37895268, 2023).
tumour (1 paper, 2024). "Multivariate linear regression analysis identified SNPs in 11 genes (Sepsecs, Rhobtb1, Tsen15, Abcc3, Arid5b, Tnr, Dock2, Tti1, Fam81a, Stx6, and Oxr1) that were independently associated with the tumour multiplicities." (PMID 39067134, 2024). "We pooled all 20 genes (Stx6, Ramp1, Traf3ip1, Nckap5, Pfkfb2, Trmt1l, Rprd1b, Rer1, Sepsecs, Rhobtb1, Tsen15, Abcc3, Arid5b, Tnr, Dock2, Tti1, Fam81a, Oxr1, Plxna2 and Tbc1d31) together as the mouse tumour susceptibility gene signature (mTSGS)." (PMID 39067134, 2024). "Multivariate analyses flagged SNPs in 20 genes (Stx6, Ramp1, Traf3ip1, Nckap5, Pfkfb2, Trmt1l, Rprd1b, Rer1, Sepsecs, Rhobtb1, Tsen15, Abcc3, Arid5b, Tnr, Dock2, Tti1, Fam81a, Oxr1, Plxna2, and Tbc1d31) independently tied to various tumour characteristics, designated as a mTSGS." (PMID 39067134, 2024).
TSEN15 also shares sentences with these, for which no sentence is quoted: cancer (1 paper); lung carcinoma (1); pontocerebellar hypoplasia (1).